RN7SL50P (RNA, 7SL, cytoplasmic 50, pseudogene)
Gene: Miscellaneous RNA gene on chromosome 18 (8,471,831 to 8,472,128, forward strand). Ensembl gene ENSG00000242985.
Homologues: Orthologues: chimpanzee Metazoa_SRP (99% identical), macaque Metazoa_SRP (91% identical). Paralogues in human: RN7SL2 (84% identical), RN7SL1 (83% identical), RN7SL543P (82% identical), RN7SL3 (81% identical), RN7SL478P (81% identical), RN7SL492P (81% identical), RN7SL451P (81% identical), RN7SL556P (81% identical), RN7SL296P (80% identical), RN7SL655P (80% identical), RN7SL797P (80% identical), RN7SL14P (80% identical), and 701 more.